MMP2 (matrix metallopeptidase 2)
Diseases named in the same sentence as MMP2 in open-access papers (continued):
Sharing a sentence is not in itself a finding about the gene and the disease.
corneal ulcer (6 papers, 2014 to 2025). Area of epithelial tissue loss from corneal surface; associated with inflammatory cells in the cornea and anterior chamber. "Other studies demonstrate the role of corneal MMPs, e.g. the involvement of MMP-2 or -9 in corneal ulceration in microbial keratitis, corneal scarring and corneal wound healing." (PMID 36701409, 2023). "This study aimed to assess the ability of subconjunctival injection of autologous PRP in the treatment of corneal ulcers in dogs and cats as well as estimate expression of MMP-2 and 9 and oxidative stress biomarkers in these patients." (PMID 33816586, 2021). "Following HSV-1 infection of the corneal epithelium, the FAK signaling pathway was activated, resulting in increased secretion of MMP-2 in the corneal tissue and accelerated formation of corneal ulcers and necrotic lesions." (PMID 24348806, 2014). "The present study investigated the secretion of MMP-2, which is directly induced by HSV-1 infection, and its association with FAK and p-FAK expression, using immunohistochemical staining and molecular biology techniques to further explore the mechanisms of corneal ulceration in HSK." (PMID 24348806, 2014). "MMP2, MMP3, and MMP9 have been previously reported to be upregulated in inflammatory/fibrotic diseases of the ocular surface, such as corneal ulcer, ocular burn, and corneal neovascularization." (PMID 35943663, 2022). "In the present study, the activity of gelatinases (MMP-2 and MMP-9) was significantly high in the corneal ulcer control positive group, which significantly decreased after treatment with autologous PRP in both dogs and cats." (PMID 33816586, 2021). "The activity percentages of both MMPs (MMP-2 and MMP-9) were significantly high in the corneal ulcer control positive group (diseased group), which significantly decreased (p ≤ 0.05) after treatment with autologous PRP treated groups in both animals." (PMID 33816586, 2021). "A previous study showed that, following HSV-1 infection of the cornea, MMP-2 (produced by corneal cells and corneal epithelial cells) plays an important role in the development of HSK-induced corneal ulceration." (PMID 24348806, 2014). "Also, an injury without bacterial infection resulted in an increase in both MMP-2 and−9 and a slight but significant downregulation of TIMP-1 in mouse corneal ulcer." (PMID 33816586, 2021).
dental caries (6 papers, 2018 to 2024). The decay of a tooth, in which it becomes softened, discolored, and/or porous. "The aim of the study was to analyse Czech children with primary/permanent dentition polymorphisms in those genes encoding MMP2, MMP3, MMP9, MMP13, MMP16, and MMP20, which had been previously associated with dental caries in other populations." (PMID 32398053, 2020). "It was suggested that fluoride, in the form of sodium fluoride, might prevent dental caries through inhibition of salivary and purified human gelatinases MMP-2 and MMP-9." (PMID 36012195, 2022). "Single nucleotide polymorphisms (SNPs) in MMP2 (rs243865), MMP9 (rs17576), MMP13 (rs2252070), and TIMP2 (rs7501477) were investigated for their association with caries in 505 subjects, 212 caries-free subjects and 293 subjects presenting with dental caries." (PMID 32116745, 2020). "During dental caries, MMPs develop proteolytic activity: MMP-20, MMP-2, -3, -9 and -8 are detected in carious dentine in dormant and active forms." (PMID 36012195, 2022). "MMP-1 (collagenase-1), MMP-2 and -9 (gelatinase-A and -B), MMP-3 (stromolysin-1), MMP-8 (collagenase-2) and MMP-20 (collagenase-3) are currently known to participate in dental caries and dental restoration failure." (PMID 36012195, 2022). "They found that human MMP-2, MMP-8, and MMP-9 were identified in demineralized dentinal lesions and inhibition of MMPs can reduce dentin caries progression." (PMID 29849633, 2018). "Allele frequencies for MMP2, MMP13 and TIMP2 polymorphisms were significantly different between individuals with or without dental caries." (PMID 32116745, 2020).
diabetic foot ulcers (6 papers, 2016 to 2025). "It was reported previously that MMP1, MMP2 and MMP9 are significantly over-expressed in diabetic fibroblasts and are important determinants of diabetic foot ulceration morbidity and exacerbation." (PMID 28423369, 2017). "Mechanisms could include the dampening of the pathologically excessive levels of collagenases (MMP-1 and MMP-8) and gelatinases (MMP-2 and MMP-9) that have been observed in biopsies of diabetic foot ulcers, compared to the levels of these proteinases seen in normal posttraumatic wounds." (PMID 27190999, 2016).
hepatic (6 papers, 2011 to 2022). "There is a common target MMP2 for hepatitis B and hepatitis C, which plays an important role in treating hepatitis with YZHG." (PMID 35342754, 2022). "The expression of MMP-2 increased significantly in moderate, severe hepatitis and cirrhotic liver (P < 0.001)." (PMID 27881141, 2016). "In moderate and severe hepatitis, a portion of HPCs expressed MMP-2 (n = 2.45 ± 0.98 per cm2 and n = 2.45 ± 0.98 per cm2, respectively)." (PMID 27881141, 2016). "Therefore, MMP2 plays an important role in HBV- and HCV-related hepatitis in the published studies." (PMID 35342754, 2022). "Our results showed that HPCs and hepatocytes in sections of mild hepatitis were negative for MMP-2." (PMID 27881141, 2016).
Hypercholesterolemia (6 papers, 2011 to 2024). An increased concentration of cholesterol in the blood. "Furthermore, VEGF and MMP-2 are responsible, at least in part, for some of the changes caused by hypercholesterolemia-derived oxidative stress." (PMID 23738034, 2013). "Previous studies showed that MMP-2 and MMP-9 were involved in coronary artery wall formation in experimental hypercholesterolemia, which coincides with vasa vasorum neovascularization." (PMID 27526687, 2016).
infertile (6 papers, 2017 to 2025). "In our previous report, we have determined the G-1575A genetic polymorphism of MMP-2 in fertile and infertile men." (PMID 29043698, 2018). "In our previous report on G-1575A MMP-2 polymorphism, we showed that the frequencies of GA genotype of fertile and infertile men were significantly different; however, the frequency of AA and GG genotypes didn’t show any significant differences." (PMID 29043698, 2018). "We also found that the frequency of individuals with both positive MMP-9 T allele and MMP-2 A allele was significantly different in the fertile group compare with the infertile individuals." (PMID 29043698, 2018). "The synergistic analysis of genotypes of C-1562T MMP-9 and G-1575A MMP-2 gene polymorphisms showed that the frequency CC/GA-combined genotype was significantly different between fertile and infertile men." (PMID 29043698, 2018). "In G-1575A MMP-2 polymorphism, the risk of infertility in individuals with AA genotype was 2.14-fold more than individuals carrying GA genotype." (PMID 29043698, 2018). "In this study we determine the prevalence of the C-1562T MMP-9 gene polymorphism and its associationwith the G-1575A of MMP-2 gene polymorphism infertile and infertile men." (PMID 29043698, 2018). "In addition, the association between C-1562T of MMP-9 and G-1575A of MMP-2 gene polymorphism in fertile and infertile men was determined." (PMID 29043698, 2018). "Of interest was the observation that MMP2 expression was elevated in the granulosa cells of older women as well as in cumulus cells from infertile poor responders." (PMID 39018235, 2024). "On the other hand, synergistic analysis of alleles G-1575A MMP-2 and C-1562T MMP-9 gene polymorphisms showed that the frequency of individuals with negative MMP-9 T allele and positive MMP-2 A allele between fertile and infertile men was significantly different." (PMID 29043698, 2018).
Inguinal hernia (6 papers, 2009 to 2023). Protrusion of the contents of the abdominal cavity through the inguinal canal. "The expression of MT1-MMP was directly correlated with MMP-2 expression, and the most intense staining was observed in patients with an inguinal hernia." (PMID 37509159, 2023). "Based on international research and our own results, we found that increase in MMP-2 activity could be considered to play a significant role in the etiology of inguinal hernias." (PMID 22481991, 2009). "For instance, MMPs (e.g., MMP‐1, MMP‐2, MMP‐9, MMP‐13) appear to be involved in inguinal hernia or recurrent inguinal hernia development." (PMID 31588690, 2019).
intracerebral hemorrhage (6 papers, 2014 to 2023). A cerebrovascular disorder characterized by bleeding into one or both cerebral hemispheres including the basal ganglia and the cerebral cortex. "Therefore, breakdown of ECM as induced by MMP2 and 9 may be associated with intracerebral hemorrhage." (PMID 26881424, 2016). "Wang and Tsirka showed that systemically intraperitoneal administration of broad-spectrum MMPs’ inhibitor (GM6001) reduces the intracerebral hemorrhage-induced gelatinolytic activity by reduction of pro- and active MMP-9 (and pro-MMP-2) proteins levels." (PMID 24918931, 2014). "Moreover, MMP-2 expression is detected in SOX2 immunopositive progenitor cells in the teleost fish, while siRNA to select MMPs abrogates enhanced neurogenesis in a murine model of intracerebral haemorrhage." (PMID 26783471, 2015).
left ventricular hypertrophy (6 papers, 2015 to 2024). Enlargement of the LEFT VENTRICLE of the heart. "In line with this, inhibition of l-NAME-dependent MMP2 activation further increased left ventricular hypertrophy as quantified by higher LV weight and NPPB expression in the LV." (PMID 39167912, 2024). "Further, they better preserved aortic endothelial function, had lower activities of matrix metalloproteinase 2 (MMP2), preserved elastin, had less fibrosis, and developed less left ventricular hypertrophy and cardiac fibrosis." (PMID 35069436, 2021).
mastitis (6 papers, 2021 to 2024). Inflammation of breast tissue during lactation or postpartum due to an obstructed duct or infection. "Luteolin inhibited the expression of TNF-α, IL-1β, and IL-6; suppressed IκBα and NF-κB p65 phosphorylation levels; and downregulated the expression of MMP-2 and MMP-9 in S. aureus-induced mastitis, showing its potential in reducing tissue damage and inflammation caused by S. aureus-induced mastitis." (PMID 36111166, 2022). "This study aimed to investigate the protein component and the activity of matrix metalloproteinase-2 (MMP-2) and -9 (MMP-9) in raw milk samples with different testing scores determined using the California mastitis test (CMT)." (PMID 37577188, 2023). "Notably, the three target genes, COL1, MMP2, and SELE, in AGE-RAGE signaling can all be affected by quercetin, which suggests that quercetin may be the most promising GYS compound for mastitis therapy." (PMID 38630770, 2024).
pancreatitis (6 papers, 2009 to 2023). Inflammation of the pancreas. "(B) qRT-PCR for Egfr, Egf, Tgfα, Mmp2 and Mmp9 expression in fibroblasts freshly sorted from control normal pancreata, iKras* pancreata 3 weeks post pancreatitis, iKras* and iKras*;CD11b-DTR pancreata 3 days post Kras* inactivation and DT treatment." (PMID 28980940, 2017). "(A) qRT-PCR for Egf, Tgfα, Hbegf, Areg, Ereg, Mmp1, Mmp2, Mmp9, Mmp12 and Mmp14 expression in littermate control, iKras* pancreata 3 weeks post pancreatitis, iKras* and iKras*;CD11b-DTR pancreata 3 days post Kras* inactivation and DT treatment." (PMID 28980940, 2017). "(C) Western-blot analysis for Collagen type I, MMP2 and β-actin in iKras* pancreata 3 weeks post pancreatitis, 3 days, 1 week upon Kras* inactivation and in iKras*;CD11b-DTR pancreata 1 week upon Kras* inactivation and DT treatment." (PMID 28980940, 2017). "When talking about DM and pancreatitis, two MMPs deserve special attention: MMP-2 and MMP-9 (gelatinases A and B, respectively), responsible for the degradation of gelatins, type III, IV, V, VII, X, and XI collagens, fibronectin, laminin, elastin, aggrecan, entactin, and vitronectin." (PMID 36830471, 2023). "Here, we showed that the mRNA level of MMP-9, but not MMP-2, was upregulated in caerulein-induced pancreatitis (data not shown), suggesting that MMP-9 plays a more predominant role during acute pancreatitis." (PMID 32411205, 2020).
Parkinson disease (6 papers, 2007 to 2025). A progressive degenerative disorder of the central nervous system characterized by loss of dopamine producing neurons in the substantia nigra and the presence of Lewy bodies in the substantia nigra and locus coeruleus. "Our results suggested that microglial activation-mediated BBB disruption via MMP-2/-9 contributed to dopaminergic neurodegeneration in rotenone-treated mice, providing a novel mechanistic insight for rotenone-elicited neurotoxicity and related Parkinsonism." (PMID 35269933, 2022).
peripheral arterial disease (6 papers, 2011 to 2023). A disorder of the arteries supplying the upper and lower extremity and the visceral organs. "Systemic concentrations of MMP-2 and MMP-9 were also increased in peripheral arterial disease and HTN, which are present in a significant proportion of patients with T2D." (PMID 34069322, 2021). "Plasma levels and zymographic activities of MMP-2 and MMP-9 are increased in T2D patients with peripheral arterial disease in comparison with healthy control subjects, and MMP-9 may be a useful marker for development of macrovascular complications in T2D." (PMID 32403389, 2020). "In addition, the expression of MMP-2 was higher in patients with type 2 DM compliant with the peripheral arterial disease compared with diabetic patients without arterial diseases and control groups." (PMID 33435900, 2021). "MMP2 and MMP9 concentrations and activities (zymography) were measured in the serum of T2D patients with or without peripheral artery disease (PAD)." (PMID 37445827, 2023).
Peritoneal Fibrosis (6 papers, 2015 to 2025). Disorder characterized by a wide range of structural changes in PERITONEUM, resulting from fibrogenic or inflammatory processes. "Effluent PAI-1 and MMP-2 represent biomarkers associated with peritoneal fibrosis and VEGF represents biomarker associated with neoangiogenesis." (PMID 31192253, 2019). "The early detection of PM dysfunction can be facilitated by biomarkers such as matrix metalloproteinase-2 (MMP-2) and tissue inhibitor of metalloproteinase-1 (TIMP-1), which are linked to peritoneal fibrosis." (PMID 40733700, 2025). "A recent study showed that administration of pioglitazone is capable of inhibiting MMP-2 activity in peritoneal fibrosis, suggesting that the MMP-2 activity is also regulated by PPAR-γ." (PMID 25970603, 2015). "Among nine DEGs, baicalein only reduced TGF-β1-induced MMP2 expression in cultured human mesothelial cells, indicating that MMP2 might be a crucial target of baicalein in alleviating peritoneal fibrosis." (PMID 37266145, 2023). "To address the role of MMP2 in peritoneal fibrosis, we silenced MMP2 by transfecting MMP2 siRNA." (PMID 37266145, 2023). "MMP2 expression increased after Chlorhexidine Gluconate-induced peritoneal fibrosis, which may be related to ECM degradation." (PMID 37266145, 2023). "Indeed, in a mice model of high-glucose based dialysis solution-induced peritoneal fibrosis, we found that the mice on PD developed peritoneal fibrosis with increased MMP2 expression, which was reversed by baicalein addition to the PD solution." (PMID 37266145, 2023). "We demonstrate that interfacing of the β1-fragment with the mesothelium of the peritoneal membrane via a biomaterial abrogates the release of active MMP2 in response to transforming growth factor β1 and rescues tissue integrity ex vivo and in vivo in a mouse model of peritoneal fibrosis." (PMID 28593951, 2017). "Therefore, targeting MMP2 may attenuate the progression of peritoneal fibrosis during PD treatment." (PMID 37266145, 2023). "Among them, MMP2, BAX, ADORA3, HIF1A, PIM1, CA12, and ALOX5 exhibited higher expression in the peritoneum with encapsulating peritoneal sclerosis compared with those in the control, which might be crucial targets of baicalein against peritoneal fibrosis." (PMID 37266145, 2023).
prostate adenocarcinoma (6 papers, 2016 to 2025). "Furthermore, DHA suppressed matrix metalloproteinase 2 (MMP2) release and reversed the myofibroblast phenotype of prostate adenocarcinoma-associated fibroblasts." (PMID 27313533, 2016). "Silybin, at 0.5 and 1% (w/w), has been reported to significantly upregulate E-cadherin and decrease the expression of the EMT markers, vimentin and MMP-2, in transgenic mice with prostate adenocarcinomas." (PMID 29875662, 2018).